ICAM1 (intercellular adhesion molecule 1)
Diseases named in the same sentence as ICAM1 in open-access papers (continued):
Sharing a sentence is not in itself a finding about the gene and the disease.
psoriasis (continued). "Deregulation of intercellular adhesion molecule-1 (ICAM-1) and vascular adhesion molecule-1 (VCAM-1) was detected in the skin and synovial membrane of patients with psoriasis and psoriatic arthritis." (PMID 24396598, 2013). "These dietary approaches can decrease levels of interleukin-6 (IL-6), vascular cell adhesion molecule-1 (VCAM-1), intercellular adhesion molecule-1 (ICAM-1), and low-density lipoprotein (LDL) in patients with psoriasis, thereby suppressing skin inflammation and abnormal keratinization." (PMID 39507900, 2024). "During the development of psoriasis phenotype in AGR129 mice after xenotransplantation, upregulation of markers such as intercellular adhesion molecule 1 (ICAM-1), MHC class II, endothelial cell adhesion molecule-1 (PEACAM-1) and pro-inflammation cytokines (TNF-α, Il-12 and IFN-γ) has been observed." (PMID 37298466, 2023). "ICAM-1 levels, on the other hand, showed no significant intergroup differences between psoriasis and control groups." (PMID 34685372, 2021). "In psoriasis involved skin, statistically significant positive correlations were found between the expression levels of PNOC and USF1 (r = 0.58, p < 0.05), PNOC and ICAM1 (r = 0.59, p < 0.05) and USF1 and ICAM1 (r = 0.51, p < 0.05)." (PMID 34884858, 2021). "We hypothesize that these lesions are unable to develop fully into psoriasis because T cell entry across the cutaneous vasculature, and T cell activation, are impaired during LFA-1/ICAM-1 blockade." (PMID 17324275, 2007). "Psoriasis and OSA also share common features such as the secretion of various mediators, including tumor necrosis factor (TNF)- α, intercellular adhesion molecule (ICAM)-1, E-selectin, and vascular endothelial growth factor (VEGF), which perpetuate inflammatory process." (PMID 40232659, 2025).
pancreatic cancer (42 papers, 2011 to 2025). "The KRAS G12D mutation, which accounts for approximately 30% of all KRAS mutations in pancreatic cancer, drives expression of ICAM1 by acinar cells in vivo a mouse model, attracting macrophages to accelerate formation of pre-cancer pancreatic lesions." (PMID 37880707, 2023). "In addition, fifteen of the proteins have been specifically linked to pancreatic cancer, including cathepsin D, glyceraldehyde-3-phosphate dehydrogenase, intercellular adhesion molecule 1, mesothelin, and tissue factor." (PMID 25987888, 2015). "MS analysis of glycopeptides captured from the surface of BxPC-3 cells revealed the presence of glycoproteins previously associated with pancreatic cancer (e.g., integrin beta-1, intercellular adhesion molecule 1) as well as novel pancreatic cancer cell-surface proteins (e.g., CD109)." (PMID 25635161, 2014). "Another study used ICAM1 as a pancreatic cancer biomarker and showed that an anti-ICAM1 antibody MRI proves to aid in the detection of aggressive and large pancreatic cancer lesions in mouse models." (PMID 40149293, 2025). "The transfection of resistant cells with ICAM-1 or ICAM-2 subsequently restored the sensitivity of pancreatic tumor cells to γδ-T-cells." (PMID 40071851, 2025). "The inhibition of PAK1 or PAK4 suppresses pancreatic cancer by stimulating anti-tumour immunity through the activation of T cells and dendritic cells through ICAM-1 and VCAM-1 upregulations." (PMID 41294859, 2025). "In the other pancreatic cancer cell lines, ICAM-1 expression was 100- to over 5000-fold lower than in HeLa cells, and it was not detectable in Beta-TC-3 cells." (PMID 39457005, 2024). "ICAM-1 and ITGB3 were found to be positively associated with CMG2 expression in pancreatic cancer cell lines at both the transcript and protein levels." (PMID 39199664, 2024). "This suggests that in the direct involvement of CMG2 in adhesion, CMG2 can also enhance adhesion through the upregulation of ICAM-1 in pancreatic cancer cells to facilitate the adhesion to HA and mesothelial cells during the dissemination to the peritoneum." (PMID 39199664, 2024). "Pancreatic cancer cells recruit PMNs through intercellular adhesion molecule-1 (ICAM-1), thereby enhancing the likelihood of cell stagnation in capillaries." (PMID 38343537, 2024). "An increased expression of ICAM-1 was seen in the pancreatic cancer cells following the overexpression of CMG2." (PMID 39199664, 2024). "When examined in an orthotopic pancreatic cancer model, the ICAM1 ADC significantly reduced tumor growth in part by reducing tumor cell proliferation." (PMID 37880707, 2023). "TGF-β1 also induces the production of ICAM-1, whose proadhesive capacity was revealed in colorectal and pancreatic cancer cells interacting with PMCs." (PMID 33921783, 2021). "Although ICAM-1 is upregulated post-irradiation in in vitro models of pancreatic cancer, it shows little change in expression in an in vivo mouse xenograft model." (PMID 32135474, 2020). "We report the identification of ICAM-1 as a potential biomarker of radiation treatment of the human pancreatic cancer cell-line PSN-1 in vitro." (PMID 32135474, 2020). "In a genetic mouse model of K-Ras-mutant pancreatic cancer, oncogenic K-Ras induced the expression of intercellular adhesion molecule-1 (ICAM-1) by pancreatic cells to attract proinflammatory macrophages, leading to increased cytokine storm in the pancreas." (PMID 30402038, 2018). "Here, the authors show that IL-35 is overexpressed by human pancreatic cancer cells and show, in a mouse model, that IL-35 promotes metastasis in an autocrine/paracrine manner via induction of ICAM-1 expression." (PMID 28102193, 2017). "In an orthotopic xenograft model, IL-35 promotes spontaneous pancreatic cancer metastasis in an ICAM1-dependent manner." (PMID 28102193, 2017).
pancreatic cancer (continued). "Recently they have also shown that under certain conditions HPMCs are capable of inhibiting growth of colorectal and pancreatic cancers in a mechanism involving the anti-adhesive capabilities of soluble ICAM-1 "." (PMID 28632775, 2017). "ICAM1 has previously been reported to be overexpressed in pancreatic cancer, and serves as an important docking point for polymorphonuclear cells that functionally promote tumor cell metastasis." (PMID 24708694, 2014). "Imaging of ICAM-1 is feasible in mouse models of pancreatic cancer." (PMID 32135474, 2020). "Similarly, down-regulation of ICAM-1 enhanced liver metastasis of pancreatic cancer." (PMID 29348824, 2017). "The expression of CAR, ICAM-1 and DAF in pancreatic tumor cell lines was quantified by real-time RT-PCR (qRT-PCR) and compared with their expression levels in HeLa cells, which are highly susceptible to all three viruses." (PMID 39457005, 2024). "RSV effectively suppressed the growth of pancreatic cancer (PaCa) in an orthotopic mouse model through the downregulation of NF-κB, cyclin D1, COX-2, intercellular adhesion molecule-1 (ICAM-1), matrix metallopeptidase-9 (MMP-9), and survivin." (PMID 32244860, 2020). "Our results demonstrate that the proadhesion molecules E-selectin, ICAM-1, and VCAM-1, the pro-inflammatory IL-1β and MCP-1, and the prometastasis gene MMP-9 are BCL-6-regulated genes in human pancreatic cancer cells." (PMID 23737761, 2013). "PAK1&4KO markedly increased ICAM-1 and VCAM-1 expression in pancreatic tumour tissues while decreasing the expression of ICAM-1 and VCAM-1 by cancer cells, indicating that PAK1&4KO upregulated the ICAM-1 and VCAM-1 in tumour stromal cells rather than the tumour cells." (PMID 41228228, 2025). "CVA21 exhibited low oncolytic efficacy in pancreatic cancer cells, likely due to a lack of or low expression of its receptor, ICAM-1." (PMID 39457005, 2024). "This was confirmed using healthy pancreatic and pancreatic cancer tissue microarrays, with no ICAM1 detected in normal pancreas and high ICAM1 expression in pancreatic cancer, with ICAM1 expression correlating with stage of disease and survival." (PMID 37880707, 2023). "However, although in vivo SPECT imaging confirms the presence of ICAM-1 in PSN-1 cells, and its suitability as a pancreatic cancer cell marker, total and radiation-mediated ICAM-1 expression is reduced in vivo compared to in vitro." (PMID 32135474, 2020). "Interestingly, PAK4KO reduced the ICAM-1 expression in pancreatic cancer cells, while the VCAM-1 expression was unaffected compared to the WT, showing that the upregulated ICAM-1 and VCAM-1 in the gemcitabine-treated PAK4KO tumours were expressed in stroma cells rather than cancer cells." (PMID 41294859, 2025). "Likewise, human pancreatic cancer cell lines lacking ICAM-1 were poorly bound and killed by γδ T cells in vitro." (PMID 37139603, 2023). "It is likely that these myeloid cells and blood borne biomarkers of pancreatic cancer act in symphony to induce some of the observed local changes in the MBH, which is confirmed by the high level of co-regulation between a number of these transcripts (e.g. lrg1, Plin4, Lcn2 and Icam1)." (PMID 35031523, 2022). "Finally, because IL-35 is not expressed in only pancreatic cancer, it may also promote the metastasis process of other cancers in an ICAM1-dependent pathway." (PMID 28102193, 2017). "Although tumour cells are also capable of expressing ICAM-1 and VCAM-1, PAK1KD did not change the ICAM-1 or VCAM-1 expressions in pancreatic cancer cells." (PMID 41294859, 2025). "In pancreatic tumour tissues, PAK4KO did not change the ICAM-1 or VCAM-1 expression in the absence of gemcitabine, nor did it affect vascular normalisation, as shown by the unchanged NG2/CD31 and α-SMA/CD31 ratios." (PMID 41294859, 2025).
pancreatic cancer (continued). "PAK4KO enhanced the expression of ICAM-1 and VCAM-1 in tumour tissues by 3 and 4 times, respectively, but not by the pancreatic cancer cells, indicating that PAK4KO specifically stimulated the expression of ICAM-1 and VCAM-1by the non-cancer stromal cells." (PMID 40943273, 2025). "They found that CA 19-9, intercellular adhesion molecule 1 (ICAM-1), and osteoprotegerin (OPG) are selective for pancreatic cancer, but not lung, breast, or colon." (PMID 28335509, 2017). "Intercellular adhesion molecule-1 (ICAM-1) is involved in the malignant progression of various human cancers, including breast, liver, renal, and pancreatic cancers, but protein stability has not been deal with in metastatic breast cancer." (PMID 29137327, 2017).
diabetic nephropathy (41 papers, 2006 to 2025). "In Malays, SLC12A3 Arg913Gln polymorphism and ICAM1 K469E (A/G) polymorphism were found to be associated with diabetic nephropathy." (PMID 37187702, 2023). "Recent studies revealed that monocyte chemoattractant protein-1 (MCP-1) and intercellular adhesion molecule-1 (ICAM-1) are overexpressed in the glomeruli from diabetic animals and has been reported to be associated with development of diabetic nephropathy." (PMID 32977573, 2020). "There is established evidence that increased ICAM-1 expression is associated with disease progression in diabetic nephropathy with its genetic deficiency proven to exert renoprotective effects." (PMID 25303153, 2014). "The aim of the present study was to determine the genetic influence of the ICAM-1 gene polymorphisms in the development of T1D and diabetic nephropathy." (PMID 16978373, 2006). "The present study aims to evaluate the genetic influence of ICAM-1 gene polymorphisms on the development of T1D and diabetic nephropathy." (PMID 16978373, 2006). "Diverse cells, including leukocytes, monocytes, and macrophages, as well as other molecules, such as chemokines (monocyte chemoattractant protein-1), adhesion molecules (intercellular adhesion molecule-1 (ICAM-1)), are implicated in processes related to diabetic nephropathy." (PMID 26106251, 2015). "Therefore, the ICAM-1 gene represents a strong positional and biological candidate for the susceptibility to the development of T1D and diabetic nephropathy." (PMID 16978373, 2006). "The present study provided evidence that SNPs rs281432(C/G) and rs5498 E469K(A/G) in the ICAM-1 gene confer susceptibility to the development of T1D and might also be associated with diabetic nephropathy in Swedish Caucasians." (PMID 16978373, 2006). "In conditions like diabetic nephropathy, increased shear stress triggers ICAM-1 expression, leading to macrophage recruitment." (PMID 40033218, 2025). "Between 2016 and 2017, diabetic nephropathy was the primary focus of these studies with angiopoietin-like protein, apolipoprotein, intercellular adhesion molecule-1, and glycation end products being the primary effectors under evaluation." (PMID 33791388, 2021). "Inflammatory cytokines, such as IL-1β and TNF-α, and chemokines, including MCP-1 and ICAM-1, have been shown to contribute to the development of diabetic nephropathy." (PMID 30841605, 2019). "Terpen glycosides from Cortex Moutan, the root bark of Paeonia suffruticosa, reduced inflammatory cytokines including IL-6, MCP-1, and intercellular adhesion molecule 1 (ICAM-1), in a rat model of diabetic nephropathy." (PMID 30274250, 2018). "Chemokines and adhesion molecules such as monocyte chemotactic protein (MCP)-1 and intercellular adhesion molecule (ICAM-1) expression are increased in diabetes nephropathy." (PMID 27527213, 2016). "Clinically, ICAM-1 and other adhesion molecules like E-selectin can predict development of diabetic nephropathy and perhaps other complications in type 1 diabetes." (PMID 25126086, 2014). "In experimental studies using T1D animal models, increased ICAM-1 expression accompanies progression of T1D and also diabetic nephropathy." (PMID 16978373, 2006). "Interestingly, genetic deficiency of ICAM-1 and/or MCP-1 protects against diabetic nephropathy by reducing the number of renal macrophages." (PMID 39867890, 2024). "Even though an increase in the level of cell adhesion molecules (ICAM-1 and VCAM-1) and selectins (E-selectin, P-selectin and L-selectin) were found during the development of diabetic nephropathy, a significant association was observed with baseline levels of VCAM-1, P-selectin and L-selectin only." (PMID 36843591, 2023). "Similarly, a model of diabetic nephropathy suggested that treatment with pioglitazone reduces glomerular sclerosis, fibrosis, and hypertrophy by lowering ICAM-1, E-selectin, and albuminuria." (PMID 36297290, 2022).
diabetic nephropathy (continued). "Furthermore, studies also finds that it can protect the kidneys of diabetic nephropathy rats and attenuate monocyte adhesion to endothelial cells induced by oxidized low-density lipoprotein by down-regulating ICAM-1." (PMID 35295335, 2022). "Inflammatory chemokines, including monocyte chemoattractant protein-1 (MCP-1) and intracellular cell adhesion molecule-1 (ICAM-1), and high-sensitivity C-reactive protein (hs-CRP) (a marker of inflammation) have been reported to be associated with the development of diabetic nephropathy." (PMID 30841605, 2019). "Inflammatory cytokines such as IL-1β, IL-18, TNF-α, MCP-1, and ICAM-1 are significantly increased in renal tissues during diabetic nephropathy and attenuating the expression of these cytokines may protect against diabetic renal injury." (PMID 26881256, 2016). "However, our data strongly supports the role of both TLR2 and 4 in regulating vascular inflammation via ICAM-1 expression in an in vivo model of diabetic nephropathy." (PMID 25303153, 2014). "Therapeutically, experimental data suggest that inhibiting ICAM-1 gene expression may prevent or slow down the development of diabetic nephropathy." (PMID 25126086, 2014). "Normally, ICAM-1 is expressed at low levels on the surface of arterial endothelial cells, but the expression at both mRNA and protein levels are significantly increased in animal models of diabetic nephropathy with T1D and T2D." (PMID 18505543, 2008). "ICAM-1 expression is related to development of T1D and diabetic nephropathy." (PMID 16978373, 2006). "Biological experiments suggest that genetic variation of the ICAM-1 gene might be involved in the development of diabetic nephropathy." (PMID 16978373, 2006). "Furthermore, according to studies using experimental models of diabetic nephropathy, there is clinical evidence that diabetic nephropathy is associated with an increase in macrophage infiltration due to upregulation of MCP-1 and intracellular adhesion molecule 1 (ICAM-1)." (PMID 39867890, 2024). "Colchicine supplementation mitigates inflammatory cell infiltration in diabetic nephropathy by inhibiting MCP-1 and ICAM-1 expression." (PMID 27527213, 2016). "Mononuclear macrophage infiltration and abnormal expression of inflammatory mediators including intercellular adhesion molecule-1 (ICAM-1), MCP-1, TGF-β1, can be observed in nephridial tissue in the early stages of diabetic nephropathy." (PMID 25880429, 2015). "Consistent with these previous reports, we observed that ICAM-1 and MCP-1 expression was increased in experimental diabetic nephropathy and that the increases were attenuated by TRLS-ext treatment." (PMID 24027593, 2013). "It is reported that ICAM-1, VCAM-1, and MCP-1 play important roles in the pathogenesis of diabetic nephropathy through inducing inflammatory cell infiltration." (PMID 24260158, 2013). "Nrf2/HO-1 axis activation and subsequent attenuation of oxidative stress strongly suppressed inflammation and downregulated intercellular adhesion molecule 1 (ICAM-1), vascular cell adhesion molecule 1 (VCAM-1), and inflammatory nitric oxide synthase (iNOS) in a mouse model of diabetic nephropathy." (PMID 36818747, 2023).